CTLA4 (cytotoxic T-lymphocyte associated protein 4)
Diseases named in the same sentence as CTLA4 in open-access papers (continued):
Sharing a sentence is not in itself a finding about the gene and the disease.
Autoimmunity (continued). "Here authors show that NBEAL2 physically interacts with CTLA-4 in human T cells, and NBEAL2 deficiency leads to reduced CTLA-4 surface expression in effector T cells, but not regulatory T cells, thus tipping the balance towards autoimmunity." (PMID 37349339, 2023). "Thus, abrogating CTLA-4 function induces autoimmunity by several mechanisms and by targeting several lymphocyte subsets." (PMID 37342323, 2023). "In fact, double-CTLA-4-knockout mice develop severe and fatal autoimmunity early in life." (PMID 37371056, 2023). "Also, the CTLA-4 gene is involved in mediating the suppressive functions of Treg (T cells regulation), in preventing autoimmunity, and its expression is also induced on activated T cells." (PMID 37568880, 2023). "The key player, CTLA-4, which was found to be defective in LRBA-deficient patients, was hypothesized to play an important role in developing autoimmunity in these patients, such as T1DM." (PMID 35453810, 2022). "Whether the application of anti-CTLA-4 antibodies in this study or a unique autoimmunity activation mechanism gives rise to this distinct irAE spectrum warrants further investigation." (PMID 35954401, 2022). "CTLA4 controls T-cell activation in several ways, which is important for protecting autoimmunity." (PMID 35494032, 2022). "Therefore, impaired function and expression of CTLA-4 results in continuous autoreactive T cells that are manifested clinically as autoimmunity." (PMID 35453810, 2022). "While a Treg specific deletion of CTLA-4 from birth causes severe autoimmunity and death, an induced deletion during adulthood displays no overt autoimmunity with a slightly enhanced resistance to experimental autoimmune encephalomyelitis." (PMID 36248808, 2022). "Acquired CTLA-4 deficiency in mice also leads to autoimmunity in several organ systems, although it does not appear to be as fatal as congenital lack of CTLA-4." (PMID 34201529, 2021). "Absence of LRBA leads to decreased CTLA-4 expression, thereby resulting in defective Treg cell function causing immune dysregulation and autoimmunity." (PMID 34248986, 2021). "Similarly, low-dose anti-CTLA4 antibody treatment in mice induces anti-parietal autoantibodies, high-dose anti-CTLA4 antibody infection leads to histologically evidence of autoimmunity." (PMID 35154081, 2021). "Heterozygous mutations in CTLA-4 lead to defects in (i) CTLA-4 ligand binding, (ii) homo-dimerization, (iii) B7-transendocytosis, and (iv) CTLA-4 vesicle trafficking, resulting in an inborn error of immunity with predominant autoimmunity." (PMID 33996698, 2021). "More specifically, CD5hi human Treg preferentially express ICOS, FOXP3, GITR, and CTLA4 similar to a subpopulation of these cells in mice that are more protective in the context of tissue‐specific autoimmunity and immune homeostasis as compared to their CD5lo counterparts." (PMID 33682083, 2021). "Inhibition of PD-1, PD-L1 and CTLA-4 activates not only tumor-specific T cells but also autoimmunity, and tumor-specific neoplastic antigens and normal tissue antigens may be cross-reactive." (PMID 34229760, 2021). "In fact, such drugs would not cause the degradation of CTLA-4 and consequently, do not interfere with Treg cells’ function in preventing autoimmunity." (PMID 33809974, 2021). "Recently, it was observed a fatal heterozygous mutation in CTLA‐4, predicted to decrease protein stability resulting in haploinsufficiency and decreased CTLA‐4 expression in a patient reporting autoimmunity (Evan’s syndrome), lymphoproliferation and severe infections." (PMID 33598480, 2021). "Reflecting their indispensable role in Treg biology, the experimental loss of function of prototypical tTreg markers like CTLA4 or CD25 causes loss of tTreg function in mice, resulting in lymphoproliferative diseases accompanied by various degrees of autoimmunity." (PMID 33532929, 2021). "CTLA-4 has a significant effect in regulating immune hemostasis and inhibition of autoimmunity." (PMID 34442365, 2021).
Autoimmunity (continued). "Finally, it investigates the impact of various MS-related treatments in the CTLA-4 and PD-L1 expression to restrain autoreactive T cells and stop the development of MS autoimmunity." (PMID 34442365, 2021). "The loss of ctla-4 in CD4+ T cells and Foxp3+ regulatory T cells was found to expand not only the effector T cells but also of CD4+Foxp3+ regulatory T cells, leading to new and unexpected insights into the function of CTLA-4 in peripheral tolerance, development of autoimmunity, and tumor immunity." (PMID 34912335, 2021). "Indeed, Treg-specific deletion of CTLA-4 results in aberrant T cell activation and autoimmunity highlighting CTLA-4 as a key functional molecule for Treg-mediated immune tolerance." (PMID 32787882, 2020). "Interestingly, the main complications during the treatment of patients with PD-1/PDL-1 blocking antibodies and with Treg-reducing CTLA-4 antibodies are autoimmune disorders that are frequently manifested in the gut." (PMID 32226027, 2020). "Previous studies have shown that CTLA-4 is only expressed on T cells and can maintain its own tolerance by inhibiting the activation and proliferation of T cells, thus protecting the body from the effects of autoimmunity." (PMID 33033520, 2020). "Individuals with the risk C allele were associated with decreased expression of DEF6 which might fail to regulate CTLA-4 availability and trafficking leading to overactivation of autoimmunity." (PMID 32566688, 2020). "As for CTLA-4, the proof that PD-1 plays a crucial role in controlling tolerance was confirmed by generating knock-out mice which developed severe strain-dependent autoimmunity, even if less harmful than that observed in CTLA-4 knock-out mice." (PMID 31060225, 2019). "The reduced CTLA-4 expression could thus be an important factor regulating autoimmunity in the Malt1-PDT mice." (PMID 31474984, 2019). "It is likely that HL12 and HL32, which was derived from an antibody identified through in vivo screening based on autoimmunity and immunotherapeutic efficacy, may have other features that needs to be explored for optimal CTLA-4 antibodies." (PMID 31267017, 2019). "Consistent with this, deficiency in PD-1 and CTLA-4 can promote spontaneous autoimmunity even on genetic backgrounds that do not usually develop autoimmune disease, although the pattern and severity do not fully overlap." (PMID 30376867, 2018). "Co-inhibitory receptors, including cytotoxic T-lymphocyte associated protein 4 (CTLA-4), programmed cell death protein 1 (PD-1), lymphocyte-activation protein 3 (Lag-3), and TIGIT play an essential role in the prevention of autoimmune disorders by promoting tolerized responses." (PMID 30564191, 2018). "The discovery that CTLA-4 initiated T cell anergy and PD-1-mediated T cell exhaustion has reframed our understanding of immunity and brought in an era of immune control in infectious diseases, autoimmunity, and cancer immunology." (PMID 30376867, 2018). "Therefore, reduced CTLA4 expression leads to reduced Treg activity, which in turn leads to autoimmunity." (PMID 28848545, 2017). "This suggests that a combination of +49G and CT60G might confer a lesser CTLA4 function, resulting in greater T-cell activity, stronger immune response, and a higher probability of autoimmunity." (PMID 27111218, 2016). "Importantly, the absence of CTLA-4 specifically on Tregs is sufficient for the development of autoimmunity, further reiterating the major role of CTLA-4 in Treg mediated suppression." (PMID 28031817, 2016). "This role is supported by the lethal lympho-proliferation and autoimmunity in CTLA-4 knockout mice." (PMID 26337719, 2015). "Besides these co-stimulatory signals, negative regulators of T-cell immunity, including CTLA-4 and PD-1, are needed in order to prevent inappropriate T-cell activation, resulting in autoimmunity." (PMID 24594636, 2014).
Autoimmunity (continued). "Interference with the processes that regulate CTLA-4 surface expression could provide an alternate therapeutic approach in the treatment of cancer and autoimmunity." (PMID 25538704, 2014). "Blockade of CTLA-4 with antibodies was shown to exacerbate disease in various mouse models of autoimmunity and could even induce autoimmune manifestations in normal mice including gastritis, oophoritis, and mild sialoadenitis." (PMID 23849743, 2013). "This suggests that in addition to lackingfunctional regulatory T cells, the CTLA-4 knockout mice also possess a lowerthreshold for activation, which may contribute to the hyper-proliferative syndromethat leads to autoimmunity in these mice." (PMID 23601194, 2013). "Importantly, genetic predisposition for the development of autoantibodies is postulated since mice expressing specific CTLA-4 isoforms developed spontaneous autoimmunity, including elevated production of autoantibodies." (PMID 23341990, 2013). "CTLA-4 on Treg is crucial for suppression of autoimmunity and for efficient anti-tumor responses." (PMID 22319577, 2012). "However its function in vivo is unclear as s-CTLA-4 expression has been reported to correlate with the occurrence of autoimmunity." (PMID 21044351, 2010). "In the cohort of patients included in the prospective autoimmune study, CTLA-4 polymorphisms were investigated in 157 out of 200 patients (48 autoimmunity group and 109 without evidence of autoimmunity)." (PMID 21044351, 2010). "The data do not support an association between SNPs in PTPN22 and CTLA-4, genes regarded as genetic master switches of autoimmunity." (PMID 19180256, 2009). "Therefore, we studied a differentiated subset of cells termed Th17, which have emerged as key mediators of autoimmunity and inflammation for their potential implication in toxicity and responses after anti-CTLA4 therapy." (PMID 19457253, 2009). "The specific mechanism whereby the C-819T and A+49G SNPs of the CTLA-4 gene promote autoimmunity in females and lead to the development of T1D is unknown." (PMID 20300303, 2008). "Another study found evidence supporting an association between CTLA-4 haplotypes and an increased risk of developing SLE, indicating that the expression and regulation of CTLA-4 could significantly affect disease progression and autoimmunity." (PMID 40282351, 2025). "However, its inhibition may simultaneously diminish harmful myeloid-driven inflammation in autoimmune disorders, contrasting with PD-1 and CTLA-4 inhibitors, which frequently aggravate or induce autoimmune symptoms." (PMID 41239350, 2025). "Cytotoxic T-lymphocyte-associated protein 4 deficiency (CTLA4-D) is an inborn error of immunity (IEI) caused by heterozygous mutations, and characterized by immune cell infiltration into the gut and other organs, leading to intestinal disease, immune dysregulation and autoimmunity." (PMID 39934899, 2025). "Notably, disrupting the interaction between CTLA-4 and B7 molecules has been shown to enhance the differentiation of Th17 cells, both in laboratory settings and in live animals, subsequently promoting Th17-mediated autoimmunity in murine models." (PMID 38375475, 2024). "Acknowledging the relative role of sCTLA-4 in health and disease may lead to distinct interpretation of many observations concerning membrane-bound CTLA-4 function, relevant across an enormous range of clinical applications including cancer, autoimmunity, allergy, and transplant biology." (PMID 38053333, 2024). "Therefore, in the context of autoimmunity, a potential drawback of CTLA-4 Ig is that although it may ameliorate inflammation by blocking CD28, it could also generate persistent, long-term memory Th17 cells by preventing exhaustion." (PMID 38226171, 2024).
Autoimmunity (continued). "As a co-stimulatory molecule on T lymphocytes, CTLA-4 is involved in the negative regulation of the immune system, which can inhibit the activation and proliferation of T cells, thus weakening the immune response, and plays an important role in the regulation of autoimmunity and anti-tumor immunity." (PMID 38802416, 2024). "The remaining patients may develop severe multiorgan autoimmunity requiring lifelong immunosuppressive treatment with Treg-sparing immunosuppression [mammalian target of rapamycin (mTOR) inhibitors] or targeted soluble CTLA-4-Ig (abatacept, belatacept)." (PMID 36636328, 2022). "Notably, the inhibitory receptors CTLA-4 and PD-1 act to constrain autoimmunity, and their inhibition has been reported to initiate or exacerbate sarcoid-like inflammation, reinforcing the notion of altered immune activation and, possibly, an autoimmune component in sarcoidosis." (PMID 36613701, 2022). "Finally, inter-individual variations in the development of irAEs for the same cancer and the same ICI regimen suggest an additional genetic background with a predisposition to autoimmunity (i.e., CTLA-4 and PDL-1 polymorphisms that are associated with autoimmune disorders." (PMID 35205703, 2022). "However, CTLA4 gene analyses do not support findings of CTLA4-linked autoimmunity as a primary determinant of the pathogenesis of endometriosis." (PMID 36142815, 2022). "However, with the general scarcity of studies investigating this topic, the clinical importance of CTLA4 autoimmunity still remains unclear." (PMID 36142815, 2022). "However, due to the low number of studies investigating this topic, the clinical importance of CTLA4 autoimmunity in endometriosis remains unclear." (PMID 36142815, 2022). "Thus, T-cells express more checkpoint inhibitors such as programmed cell death-ligand 1 (PD-1) and cytotoxic T lymphocyte-associated antigen-4 (CTLA-4), exhibit poor antigen response to avoid autoimmunity, and enter a quiescence state also known as T-cell exhaustion." (PMID 35681656, 2022). "In a recent study, abatacept was administered in children with refractory AIHA following HSCT showing favorable efficacy and safety and indicating that the CTLA4 pathway is likely involved in autoimmunity even without genetic mutations in the corresponding gene." (PMID 33435309, 2021). "Under homeostatic conditions, the upregulation of cytotoxic T lymphocyte associated protein 4 (CTLA4), programmed cell death protein 1 (PD1), and other immune checkpoints helps to enforce peripheral tolerance by preventing immune-activation by self-antigens, thereby limiting autoimmunity." (PMID 34868044, 2021). "As CTLA4 is known to be associated with T1D, alterations in EHMT2 expression and/or function owing to natural variations may as well be linked to autoimmunity." (PMID 34220961, 2021). "Due to interaction with CTLA-4, there is partial resemblance in immunological and clinical presentation of these two conditions with presentations including hypogammaglobulinemia, recurrent infections, and autoimmunity such as enteropathy, AIC, and polyendocrinopathy." (PMID 34248986, 2021). "Indeed, immune-related toxicity may appear as an outcome of PD-1/PD-L1 or CTLA-4 blockage, which directly halts the immune recognition, or secondarily promotes the acquisition of autoimmunity." (PMID 33266109, 2020). "Consequently, defects in CTLA-4 protein expression or trafficking pathways result in immune dysregulation, as evidenced by CTLA-4 haploinsufficiency in humans and Ctla4−/− mice—both of which show decreased frequency of Tregs, multiorgan lymphocytic infiltration, and autoimmunity." (PMID 31156616, 2019). "One would have expected that T cell-mediated autoimmunity might involve aberrant expression of co-signaling receptors, with increased expression of co-stimulatory (e.g., CD28) and downregulation of co-inhibitory checkpoint (e.g., PD-1 and CTLA-4) molecules in autoimmunity." (PMID 29489833, 2018).
Autoimmunity (continued). "The recent development of checkpoint inhibitors such as ipilimumab targeting CTLA-4 and nivolumab targeting PD-1 provide further opportunities to enhance antitumor immune response with the potential to produce durable clinical responses though opportunistic autoimmunity." (PMID 29312333, 2017). "Functionally, CTLA-4 attenuates T-cell signaling by interference with intracellular signal transduction events, including TCR signaling, and reduced CTLA-4 expression and/or activity results in uncontrolled T-cell-associated autoimmunity and lymphoproliferative disease." (PMID 24991555, 2014). "Our results establish a critical link between CTLA4 endocytosis and UCP2-mediated metabolic shift in Tregs and identified UCP2 as a potential therapeutic target for preventing RA autoimmunity." (PMID 41068616, 2025). "Immune inhibitory surface proteins such as CTLA4, CD47, and SIRPα, among many others, provide a means for limiting autoimmunity." (PMID 38543910, 2024). "Expression of ICP such as: CTLA4, PD1, LAG3, and TIM3 regulates prolonged activation of T-cells by maintaining peripheral tolerance and preventing autoimmunity." (PMID 37104271, 2023). "On the other hand, patients with defects in CTLA-4 or LRBA gene present with life-threatening immune dysregulation, autoimmunity and lymphocytic infiltration of multiple organs." (PMID 37767915, 2023). "The human leukocyte antigen (HLA), CTLA4, and PTPN22 as T-cell activation regulators are suspected of playing a key role in autoimmunity processes, i.e., the aberrant function of the molecules encoded by them may be responsible for the development of autoimmunity." (PMID 34999914, 2022). "Although this finding from the mouse model cannot be translated directly into humans, it is possible that the anti-CTLA4 antibody may exert the same suppressive effect on Tregs in humans, leading to potential severe side effects due to reduction of self-tolerance and thus increased autoimmunity." (PMID 36142815, 2022). "Inhibitory signals triggered by the programmed death receptor 1 (PD-1), and the cytotoxic T-lymphocyte protein 4 (CTLA-4) also control the intensity of T-cell response, which is important to mitigate autoimmunity and allowing peripheral tolerance." (PMID 35327589, 2022). "CTLA-4 serves as a key functional molecule for Treg-mediated immune tolerance, and Treg-specific deletion of CTLA-4 leads to aberrant T-cell activation and autoimmunity." (PMID 35559250, 2022). "Firstly, clinical apparent autoimmunity, in general, appears to be more prevalent in humans with CTLA-4 haploinsufficiency compared with patients receiving CTLA-4 pharmacological blockade." (PMID 35912205, 2022). "The importance of CTLA‐4 trafficking to its function has been recently highlighted in individuals defective in a protein, LRBA, who develop early‐onset autoimmunity." (PMID 33960403, 2021). "However, since CTLA-4 is likely expressed by human B-1a cells, our studies suggest that the dysfunction of human B-1a if/when they loss CTLA-4 regulation may contribute to the autoimmunity observed in patients receiving CTLA-4 blockade immunotherapy." (PMID 33483505, 2021). "Functional CTLA4 deficiency, whether due to CTLA4 haploinsufficiency, LRBA deficiency or DEF6 deficiency, may be suspected in cases with lymphoproliferation (38–73%) and granulomatous disorders (17–45%) associated with complex autoimmunity (mainly cytopenias) and inflammatory enteropathy." (PMID 34359324, 2021). "All PRKCD, CTLA4, TET2 and NRAS/KRAS patients presented clinically with lymphoproliferation and autoimmunity, considering all those reported cases (n=197) as ALPS-like patients." (PMID 34447369, 2021). "Our findings are also consistent with the fact that CTLA-4 and PD1 blockade, both of which increase CD28 signals, are known to trigger autoimmunity." (PMID 33223527, 2020). "Indeed, some data suggests that variation in the CTLA-4 gene may promote autoimmunity." (PMID 32411136, 2020).